LEP (leptin)
Diseases named in the same sentence as LEP in open-access papers (continued):
Sharing a sentence is not in itself a finding about the gene and the disease.
COVID-19 (continued). "Several studies provided insights on chemerin, adiponectin, leptin, resistin, and galectin-3 levels in SARS-CoV-2-infected patients, while limited information is yet available on the adipokines apelin and visfatin in COVID-19." (PMID 37238973, 2023). "A prospective study with 195 hospitalized COVID-19 patients did not observe different plasma leptin levels between patients not admitted and those admitted to the intensive care unit, and between survivors and non-survivors." (PMID 37238973, 2023). "The Adiponectin to Leptin (Adpn/Lep) ratio, a marker of adipose tissue dysfunction, was similarly reduced in all hospitalized COVID-19 and non-COVID critical patients compared to mild COVID-19 and healthy controls." (PMID 36509969, 2023). "The leptin (LEP) gene showed the highest upregulation level both in virus-positive and in virus-negative COVID-19 cases (FC = 6.07, FDR = 0.009 and FC = 6.28, FDR = 0.003, respectively)." (PMID 37246981, 2023). "Systemic leptin levels were found to be increased in SARS-CoV-2-infected patients, but associations with COVID-19 disease severity were not consistently observed." (PMID 37238973, 2023). "In our study, we did not observe significant differences in leptin levels between COVID-19 and healthy patients probably due to only slightly elevated body mass and BMI values in both groups." (PMID 37240656, 2023). "It would be reasonable to determine the level of ghrelin and leptin in patients with different courses of SARS-CoV2 infection (mild and severe), which would probably shed more light on the role of ghrelin and leptin in the immune response in COVID-19 patients." (PMID 37240656, 2023). "Here, leptin levels were similar in patients with COVID-19 and non-COVID-19 suffering from severe pneumonia, and were neither related to the inflammatory cytokines measured or the disease outcome." (PMID 37238973, 2023). "In severe, but not critical COVID-19 patients, we found that plasma Leptin, Resistin and IL-6 correlated with the fraction of inspired oxygen (FiO2) but not the length of hospital stay." (PMID 36509969, 2023). "Taking into account only slightly elevated BMI values and a mild course of SARS-CoV2 infection in our COVID-19 group, it seems that leptin levels in such populations of patients have no significant impact on COVID-19 outcomes." (PMID 37240656, 2023). "To verify if the lack of activated phenotype in the presence of adipokines was not leptin-specific, we exposed endothelial cells to plasma obtained from critically ill obese COVID-19 patients." (PMID 35837388, 2022). "Our main finding was that plasma leptin was higher in COVID-19 patients than in healthy controls, but without relation to the severity of COVID-19." (PMID 35052684, 2021). "A small study demonstrated that COVID-19 patients who needed mechanical ventilation had significantly higher serum/blood leptin levels compared to a control group without the need for mechanical ventilation." (PMID 33824998, 2021). "This suggests that leptin may function as an inflammatory mediator in some situations but not in others, such as COVID-19." (PMID 39200926, 2024). "Leptin levels were higher in the plasma from severe and critical COVID-19 patients during the second wave, [8.4; IQR 3.3–16.9] compared to the first wave [17.4; IQR 7.9–40.0] for severe, and [9.5; IQR 5.9–51.0] compared to [4.0; IQR 1.9–9.6] for critical COVID-19 patients." (PMID 36509969, 2023). "While this may suggest that serum leptin concentrations decline in advanced COVID-19 disease, this finding was not related to survival in critical COVID-19 patients." (PMID 37238973, 2023). "In contrast, leptin levels were not significantly different between clinical severity categories, although they also tended to be lower in patients with moderate and severe acute COVID-19 as compared to individuals who suffered from mild acute COVID-19." (PMID 36788324, 2023).
COVID-19 (continued). "Some studies also compared leptin levels between comparably ill patients with and without COVID-19." (PMID 37238973, 2023). "Although this adds to the reports pointing to elevated leptin levels being indicative of a SARS-CoV-2 infection; the implications of this study are limited due to the higher BMI of the COVID-19 patients, which may well explain higher serum leptin levels irrespective of the SARS-CoV-2 infection." (PMID 37238973, 2023). "Moreover, most of these correlations were lost in critical COVID-19 patients except the negative correlation of IL-6 with leptin levels, and positive correlations found between IL-10 and TNFα and Resistin." (PMID 36509969, 2023). "Notably, the presence of leptin or plasma from obese critically ill COVID-19 patients did not alter this phenotype." (PMID 35837388, 2022). "Lastly, since leptin is not the only systemic adipokine abundantly present in the blood of obese individuals, we investigated endothelial activation to plasma obtained from obese critically ill COVID-19 patients." (PMID 35837388, 2022). "However, there are several puzzling factors regarding leptin as a biomarker in COVID-19, e.g., both coronavirus SARS-CoV-2 and leptin exert inflammatory reactions involving the endothelial vascular surfaces, which could potentially act in synergy." (PMID 35052684, 2021). "Therefore, leptin may act as an inflammatory mediator in some conditions but not in others such as COVID-19." (PMID 36509969, 2023). "Furthermore, adding to the uncertainty in the field, another study could not detect major differences in plasma leptin levels between healthy controls and patients with mild, severe, and critical COVID-19." (PMID 37238973, 2023). "Levels of IL-6, leptin and adiponectin were determined at baseline and compared between groups, in order to test the hypothesis that proinflammatory adipokines are higher in patients with COVID-19 with MetS compared with those without MetS." (PMID 33328246, 2020). "When leptin was included as a conditional factor in the BMI to COVID-19 severity MR model through MVMR, the direct effect of BMI (26 SNPs) on COVID-19 severity was no longer statistically significant (OR = 0.9839; 95% CI: 0.752–1.216)." (PMID 41359762, 2025). "We measured leptin in patients only at admission to ICU, but not in patients with COVID-19 who, for various reasons, were not ICU treated." (PMID 35052684, 2021). "Women had higher plasma levels of leptin than men, when admitted to ICU, which has never previously been described in COVID-19." (PMID 35052684, 2021). "Neither median duration of COVID-19 before admission to ICU (10 days; IQR = 4) or median length of ICU stay (8 days; IQR = 11) correlated with the plasma leptin levels." (PMID 35052684, 2021).
Impaired glucose tolerance (77 papers, 2004 to 2026). An abnormal resistance to glucose, i.e., a reduction in the ability to maintain glucose levels in the blood stream within normal limits following oral or intravenous administration of glucose. "they found that in women with impaired glucose tolerance, placental leptin gene DNA methylation levels were associated with maternal 2-h glucose levels." (PMID 35002980, 2021). "We also reported that POMC neuron deficiency of Src homology-2 tyrosine phosphatase (Shp2), a major intracellular signaling pathway for leptin, was associated with impaired glucose tolerance and marked attenuation of leptin’s effects to lower plasma glucose and insulin." (PMID 29190687, 2017). "SAMP8 mice fed an HFD exhibited increased body weight, impaired glucose tolerance, and elevated serum leptin levels." (PMID 39984825, 2025). "Independent of genotype, consumption of HF, but not HS, diet increased energy intake, body weight, and plasma leptin, and impaired glucose tolerance." (PMID 35557971, 2022). "A similar study reported that sardine protein lowered plasma leptin and glucose levels and improved impaired glucose tolerance." (PMID 31382619, 2019). "And the increased glucose, HbA1c level, and leptin concentration were found in both of diabetic rat, which exhibited impaired glucose tolerance." (PMID 30622594, 2018). "Also, both control and high-fat diets detected increased BW and adiposity, reduced energy expenditure, increased leptin levels, and impaired glucose tolerance in female mice." (PMID 37790202, 2023). "The study reported adaptations in DNA methylation of the leptin gene in mothers with gestational impaired glucose tolerance, which suggested that the epigenetic profile of leptin may be influenced by maternal plasma glucose levels." (PMID 29642382, 2018). "Moreover the mice fed a HFD were obese and showed an impaired glucose tolerance and a leptin upregulation." (PMID 26229237, 2015). "Young male Wistar rats fed HCHF diet showed progressive increases in body weight, abdominal fat deposition, and whole body fat mass along with impaired glucose tolerance, plasma lipid abnormalities, hyperinsulinaemia, and increased plasma leptin concentrations." (PMID 22007192, 2012). "Sleep deprivation has several adverse physiological consequences, including impaired glucose tolerance and insulin sensitivity, elevated sympathetic tone, increased inflammation, and the increase of ghrelin and the decrease of leptin with the subsequent increase of hunger and appetite." (PMID 20920190, 2010). "A partial sleep deprivation (4 hours per night for 6 consecutive nights) may trigger impaired glucose tolerance, higher evening secretion of cortisol, increased sympathetic nervous system activity, and reduced leptin (the appetite suppressant) secretion and might produce a prediabetic state." (PMID 22363869, 2011). "Although leptin seems to be regulated physiologically, low leptin levels may contribute to sexual disturbances, impaired glucose tolerance, and higher frequency of pulmonary infection, observed in COPD patients, while leptin has been associated with the presence of osteoporosis in COPD subjects." (PMID 21040518, 2010). "Hypothalamic VGF expression has been shown to be regulated by both feed restriction and leptin, with VGF knockout mice displaying increased adiposity, reduced energy expenditure and impaired glucose tolerance." (PMID 39095703, 2024). "SCAT and VAT LEP mRNA expression were not significantly different across participants with normal or impaired glucose tolerance and T2D, independent of sex." (PMID 36833305, 2023). "The obese phenotype at P21 was related to elevated serum concentration of leptin, but not of insulin, and an impaired glucose tolerance when compared to IL-6−/−SD." (PMID 35896539, 2022). "We also confirmed impaired glucose tolerance, increased levels of leptin and nonesterified fatty acids, and decreased levels of HDL-C in the serum of the HTG rats." (PMID 33467512, 2021).
Impaired glucose tolerance (continued). "Feeding a red algae (GA) diet has been shown to significantly decrease plasma TNF-α, leptin, and TC/TG levels, but not affect the weights of body, liver, and adipose tissue, in a high fructose diet-impaired glucose tolerance rat model." (PMID 31540318, 2019). "The results demonstrated that mice on the high-fat diet increased weight gain and showed higher blood concentrations of glucose, insulin, and leptin, as well as impaired glucose tolerance and pancreatic β-cell function relative to those on the normal control diet." (PMID 33322303, 2020).
colorectal cancer (76 papers, 2010 to 2026). A primary or metastatic malignant neoplasm that affects the colon or rectum. "Association of resistin, leptin, adiponectin, and visfatin with the development of colorectal cancer." (PMID 39184804, 2024). "In colorectal cancer, high leptin levels are associated with lymph node involvement, microvascular invasion, and advanced tumor stage." (PMID 38255203, 2024). "By far, some of the mechanisms underlying the phenomenon of elevated intratumoral leptin expression have been investigated in breast and colorectal cancers." (PMID 35778755, 2022). "We quantified the mediating roles of C‐reactive protein (CRP), leptin, fasting insulin, and estradiol in the effect of adiposity on estrogen receptor (ER)‐positive breast, endometrial, and colorectal cancer risk in postmenopausal women." (PMID 35048536, 2022). "Circulating levels of leptin have been evaluated in at least seven prospective studies of colorectal cancer, of which four have shown a positive association, consistent with our present study." (PMID 32053666, 2020). "In this prospective case-control study, we observed a statistically significant association of SNPs in the FTO gene and plasma leptin levels with the incidence of colorectal cancer." (PMID 32053666, 2020). "Additional adjustment for BMI considerably attenuated the associations of plasma adipokines with the risk of colorectal cancer, but an elevated risk was still statistically significant for plasma leptin levels." (PMID 32053666, 2020). "Plasma leptin levels were positively associated with the incidence of colorectal cancer (Ptrend = 0.04), with a multivariate adjusted OR of colorectal cancer for the highest compared to the lowest quintile of 1.80 (95% CI, 1.12–2.88)." (PMID 32053666, 2020). "Associations of candidate leptin variants with colorectal cancer among post-menopausal women, by duration of estrogen-only hormone replacement therapy use." (PMID 30379922, 2018). "A recent meta-analysis was conducted to analyze the association of circulating leptin and both colorectal adenoma and colorectal cancer." (PMID 25197277, 2014). "Another nested case-control study conducted in Norway demonstrated that men with top quartile leptin level presented 2.28–fold increased colorectal cancer risk in comparison with three bottom quartiles." (PMID 23593308, 2013). "This study systematically evaluated the association between a set of polymorphisms in the Leptin gene family and colorectal cancer risk in a two-stage case-control study." (PMID 23593308, 2013). "Recently, epidemiologic evidence has demonstrated the positive association between serum leptin and colorectal cancer risk." (PMID 23593308, 2013). "The association between leptin levels and the risk of colorectal cancer or adenoma has remained controversial." (PMID 21254741, 2010). "Leptin significantly increases tumor necrosis factor alpha (TNF-α) secretion through the activation of p38 and JNK/MAPK and TNF-α can induce cancer invasion and metastasis associated with EMT in colorectal cancer, suggesting a potential effect of leptin on EMT in colorectal cancer as well." (PMID 37686525, 2023). "High leptin expression is associated with a better outcome of colorectal cancer patients." (PMID 35628510, 2022). "In a subgroup analysis conducted by cancer type and cancer system, we obtained significant results that the LEP G19A polymorphism may decrease the risk of colorectal cancer, esophageal cancer, digestive system cancer, and urinary system cancer." (PMID 34868961, 2021). "In conclusion, this meta-analysis suggests that the LEP G19A mutation may decrease the risk of overall cancer, colorectal cancer, esophageal cancer, digestive system cancer, and urinary system cancer." (PMID 34868961, 2021). "Similarly, in a WHI case‐cohort study, a positive association between serum leptin concentration and colorectal cancer risk was found, even after adjustment for insulin concentrations." (PMID 33038280, 2021).
colorectal cancer (continued). "Therefore, high leptin favors cancer growth and the relationship between circulating leptin concentrations and colorectal cancer risk has been demonstrated." (PMID 30845725, 2019). "A case-control study conducted in Japan showed that, female with serum leptin level in quintile 2 and 3 combined, and quintile 4 and 5 combined harbored 1.40–fold and 4.84–fold increased colorectal cancer risk when compared with the lowest quintile, respectively." (PMID 23593308, 2013). "In a clinical study of colorectal cancer, leptin expression was associated with tumor G2 grade." (PMID 21338489, 2011). "Furthermore, several studies have investigated the protein expression pattern of LEP in tissues of many cancer types such as breast and colorectal cancer, but only one study had assessed the clinical value of LEP and its associated receptor (Ob-R) in OC patients from the Middle-East region." (PMID 34884678, 2021). "Inflammatory biomarkers, including CRP, IL-6, TNF - α and its receptors, adiponectin and leptin, play complex roles in colorectal cancer development." (PMID 39980561, 2025). "We examined the relevance of genetic variants of LEP and leptin receptor (LEPR) to colorectal cancer (CRC) survival by using data from the Newfoundland Familial Colorectal Cancer Study." (PMID 37282602, 2023). "The aim of the study was to assess the concentration of leptin in the blood serum as well as the expression of the leptin receptor in colorectal cancer cells." (PMID 36981858, 2023). "Leptin levels were also correlated with a better prognosis in patients with colorectal cancer and leptin was reported to inhibit hepatocellular carcinoma proliferation in vitro through the p38-MAPK-dependent signaling pathway." (PMID 36674935, 2023). "In the current study, we observed differences in the leptin–adiponectin ratio which were in agreement with data from the Spanish review wherean increased leptin–adiponectin ratio correlated with tumor TNM stages in colorectal cancer." (PMID 37444627, 2023). "Aim of the Paper: The aim of the study was to assess the concentration of leptin in the blood serum as well as the expression of the leptin receptor in colorectal cancer cells." (PMID 36981858, 2023). "Several investigators have demonstrated that leptin circulating levels were significantly higher in colorectal cancer patients." (PMID 37509120, 2023). "A recent colorectal cancer case–control study related to polymorphisms revealed the association of LEPR rs6588147 and rs1137101, as well as LEP rs2167270, with lower cancer risk, whereas LEPR rs1137100 was associated with cancer susceptibility." (PMID 35563103, 2022). "Here, we quantified the roles of leptin and C‐reactive protein, fasting insulin, and estradiol in explaining the effect of high BMI on estrogen receptor‐positive breast, endometrial, and colorectal cancers in postmenopausal women." (PMID 35048536, 2022). "For colorectal cancer, there was evidence for mediating effect through fasting insulin, while the point estimates for indirect effects through leptin and CRP, and estradiol were essentially null." (PMID 35048536, 2022). "Leptin is found to upregulate MPS-1 in colorectal cancer cells that further promoted the cell survival and proliferation via activating JNK/c-JUN signaling." (PMID 34588926, 2021). "A total of 32 blood samples from colorectal cancer patients and 25 healthy subjects were analyzed for serum levels of leptin." (PMID 33799880, 2021). "In a colorectal cancer cohort of 1003 cases and 1303 matched controls, LEPR rs6588147, rs1137101, and LEP rs2167270 polymorphisms were found to be associated with a decrease in cancer risk, whereas LEPR rs1137100 was associated with cancer susceptibility." (PMID 33799880, 2021). "Current mechanisms suggest that Leptin plays a role in colorectal carcinoma cells through PI3K/Akt and mTOR pathway regulation and invasion, as well as those implicated in the JAK2, STAT3, and NF-kB pathways." (PMID 34842660, 2021).